BRAF (B-Raf proto-oncogene, serine/threonine kinase)
Diseases named in the same sentence as BRAF in open-access papers (continued):
Sharing a sentence is not in itself a finding about the gene and the disease.
colorectal cancer (continued). "Role of KRAS, BRAF and PIK3CA mutations in pathogenesis of colorectal cancer (CRC) has been recently investigated worldwide." (PMID 22931052, 2012). "In 23 out of 48 colorectal cancer cases with microsatellite instability (MSI-high; 48%), a BRAF mutation in exon 15 was present, compared to only 10 out of 131 (8%) of the MSS/MSI-low tumors (P = 8.9E-9)." (PMID 21777459, 2011). "It has been reported that primary colorectal cancers, which showed KRAS or BRAF mutations, also frequently showed RASSF2 methylation, and inactivation of RASSF2 enhanced KRAS-induced oncogenic transformation." (PMID 20920251, 2010). "KRAS, BRAF/KRAS, and LKB/KRAS mutation(s) are correlated with sensitivity to MEK inhibitors in ovarian cancer, colorectal cancer, and NSCLC, respectively." (PMID 21124782, 2010). "BRAF and K-ras proto-oncogenes encode components of the ERK signalling pathway and are frequently mutated in colorectal cancer." (PMID 20233436, 2010). "Among the most harmful of all genetic abnormalities that appear in colorectal cancer (CRC) development are mutations of KRAS and its downstream effector BRAF as they result in abnormal extracellular signal-related kinase (ERK) signaling." (PMID 20942929, 2010). "Overview of studies that examined the clinical validity of testing for BRAF p.Val600Glu for assessment of treatment options for colorectal cancer (CRC)." (PMID 20972475, 2010). "On one hand IGFBP7 has recently been described as a tumour suppressor gene in colorectal cancer and was shown to induce senescence in cells harbouring oncogenic BRAF, whereas on the other hand IGFBP7 was shown to have oncogenic properties in gliomas." (PMID 20579385, 2010). "KRAS mutations occur most frequently in 30–40% of all colorectal cancers and BRAF mutations are present at a frequency of 5–22%, in which the constitutively activated BRAFV600E variant accounts for ∼90% of all the BRAF mutations." (PMID 20027224, 2009). "The analysis of primary tumours revealed K-Ras mutations in 43% of cases, BRAF mutations in 6% of cases and PTEN loss of expression in 21% of cases, in agreement with the earlier data concerning sporadic colorectal cancers." (PMID 19293803, 2009). "Concerning the frequency of BRAF alterations in colorectal carcinomas, 14 of the 50 (28%) MSI and 4 of the 53 (7.5%) in MSS colorectal tumours show BRAF mutations." (PMID 18782444, 2008). "The CpG island methylator phenotype (CIMP) with widespread promoter methylation is a distinct epigenetic phenotype in colorectal cancer, associated with microsatellite instability-high (MSI-high) and BRAF mutations." (PMID 17474983, 2007). "Clinicopathological and molecular features of BRAF mutant colorectal cancers stratified according to methylator phenotype status." (PMID 16403224, 2006). "Clinicopathological and molecular features of BRAF mutant colorectal cancers stratified according to microsatellite instability status." (PMID 16403224, 2006). "A prominent example is the mutually exclusive occurrence of the BRAF hotspot mutation (V600E) and KRAS mutations in colorectal cancer." (PMID 15784156, 2005). "In an evaluation of 45 clinical tumor RNA specimens spanning pancreatic, cholangiocarcinoma, and colorectal cancers, the assay correctly classified mutation status with full concordance for KRAS G12D, IDH1 R132C and BRAF V600E, with a subset of positive cases corroborated by orthogonal RT-ddPCR." (PMID 42080370, 2026). "BRAF mutations are present in several non-melanoma cancers, including colorectal cancers, non-small-cell lung cancers, hairy-cell leukemia, multiple myeloma as well as LCH." (PMID 38376733, 2025).
colorectal cancer (continued). "A basket trial assessing the efficacy of the BRAF inhibitor, vemurafenib, exemplifies the importance of TOO; despite most cases carrying the BRAF V600E mutation, response rates varied widely; 0% in colorectal cancer, to 12% in cholangiocarcinoma, and 42% in NSCLC." (PMID 40615718, 2025). "Compared to existing molecular tools for colorectal cancer staging—such as APC, KRAS, BRAF, NRAS and PIK3CA mutations—our study offers a novel transcriptomic perspective by identifying stage-specific gene expression signatures that distinguish adenoma, CIS and adenocarcinoma." (PMID 40362431, 2025). "Additionally, pyrotinib combined with trastuzumab has shown antitumor activity in ERBB2 (HER2)-positive RAS/BRAF wild-type advanced colorectal cancer." (PMID 41413856, 2025). "This paradox highlights the need for a comprehensive investigation, which could provide novel insights into improving the efficacy of immunotherapy in BRAF V600E-mutant colorectal cancer." (PMID 39934467, 2025). "In colorectal cancer, RAS and BRAF are major mutation points in the RAS-MAPK signaling pathway." (PMID 40546348, 2025). "BRAF mutations are also observed in various non-melanoma cancers, including colorectal cancers, non-small-cell lung cancers, hairy-cell leukemia, multiple myeloma, and LCH." (PMID 38376733, 2025). "Importantly, using machine learning algorithms, we identified IDO1 as a potential immunotherapy target in BRAF V600E-mutant colorectal cancer, offering a new strategy for treatment." (PMID 39934467, 2025). "This modest attenuation suggests that part of the effect of BRAF p.V600E on colorectal cancer-specific death may be due to its role in advancing the progression of cancer to a more advanced stage." (PMID 41413856, 2025). "The pan-cancer expression levels were analyzed from PANDA transcriptome data featuring patient status in colorectal cancer samples highlighted in red box, where BRAF was overexpressed compared to adjacent normal tissues, with a p-value significance code of <0.05." (PMID 41009348, 2025). "WT BRAF colorectal cancers within the combined cohort are included for reference." (PMID 39751654, 2025). "Additionally, in colorectal cancer, RNF43 mutations have been shown to predict response to combined anti-BRAF/EGFR therapies, further highlighting the therapeutic relevance of this alteration across tumor types." (PMID 40735046, 2025). "We further obtained archival tumor material from two BRAF–Ras double-mutant colorectal cancers." (PMID 39751654, 2025). "Co-mutations in BRAF and PIK3CA may signify an aggressive phenotype, as both mutations correlate with poor outcomes in colorectal cancer." (PMID 40502411, 2025). "Low HMGA2 expression was also linked to microsatellite instability (p = 0.0002) and BRAF mutations (p = 0.0018) as well as absence of RAS mutations (p < 0.0001) in colorectal cancer and HPV infection in squamous cell carcinomas (p < 0.0001)." (PMID 40518465, 2025). "Initially, we confirmed longer OS for class 3 than for class 1 BRAF-mutant colorectal cancers without concomitant pathogenic Ras pathway mutations (HR = 0.25; P = 0.011)." (PMID 39751654, 2025). "2.we found that colorectal cancer patients with HER-2 amplification have a shorter duration of response to EGFR monoclonal antibody therapy and worse prognosis compared to those with wild-type RAS/BRAF, approaching even those with RAS or BRAF mutations." (PMID 40308511, 2025). "This study evaluated BRAF IHC staining quality and interpretation in general pathology laboratories through a nationwide proficiency test (PT) in Taiwan, focusing on the most commonly encountered thyroid neoplasm and colorectal cancer." (PMID 40689945, 2025).
colorectal cancer (continued). "In contrast, mutations in the APC are uncommon in the serrated colorectal cancer (SCC) pathway, which is initiated by activating mutations in BRAF or KRAS and usually progresses to malignancy through a plethora of epigenetic alterations, microsatellite instability and MLH1 hypermethylation." (PMID 40357363, 2025). "However, the current molecular markers, such as BRAF mutations, fail to stratify the prognostic and therapeutic heterogeneity within dMMR/MSI colorectal cancers." (PMID 40824763, 2025). "However, consistent with other findings, POLE-mutated colorectal cancers were significantly associated with younger age, right-sided colon location, poor histological grade, early stage, and KRAS/NRAS/BRAF wild-type status." (PMID 40310397, 2025). "Notably, we also identified IDO1 as a potentially immunotherapy target for patients with BRAF V600E-mutant colorectal cancer." (PMID 39934467, 2025). "Recently, BRAF V600E has become an actionable target in colorectal cancer." (PMID 40731762, 2025). "Notably, HSPA8 inhibitor VER155008 sensitizes BRAF V600E colorectal cancer to targeted drugs, which offers potential therapeutic strategies." (PMID 37973552, 2024). "In addition, we showed that, among BRAF‐wild‐type cases, both KRAS c.34G>T (p.G12C) mutation and KRAS mutations other than c.34G>T were associated with higher colorectal cancer‐specific mortality compared with KRAS‐wild‐type cases." (PMID 39039804, 2024). "Similarly to BRAF V600 inhibitors, these drugs appear to be more efficacious for colorectal cancer when administered in combination with anti-EGFR antibodies." (PMID 38612902, 2024). "For instance, non-small-cell lung cancer requires the presence of EGFR, ALK, ROS1, BRAF, MET, RET, and KRAS genes, while the prognosis of colorectal cancer patients can be determined by the mutation of KRAS, NRAS, BRAF, and HER2 genes, as well as microsatellite instability analysis." (PMID 39194571, 2024). "In colorectal cancer, the mutation of KRAS or BRAF genes could increase the expression level of glucose transporter‐1 (GLUT1) and enhance glycolysis." (PMID 38613347, 2024). "Despite the small sample size and the reference studies, the BRAF status could be considered a predictive biomarker of 5-fluorouracil treatment in colorectal cancer." (PMID 38248103, 2024). "We hypothesize some correlation between BRAF mutation and SMARCB1-defcient features in colorectal cancers." (PMID 38217014, 2024). "To determine novel pathways associated with constitutively active V600EBRAF and novel therapeutic strategies, we calculated hallmark pathway mean Z-scores using the publicly available GSE59857 BRAFMT and BRAF/KRASWT colorectal cancer dataset and the ssGSEA method." (PMID 39083088, 2024). "In conclusion, we identified BRAF as a biomarker for response to BOLD-100 in colorectal cancer." (PMID 39083088, 2024). "Furthermore, small-molecule inhibitors of ERK either show no efficacy or produce a partial clinical response in patients with KRAS- and BRAF-mutant colorectal cancer." (PMID 38277448, 2024). "Consequently, the clinical use of BRAF V600E inhibitors in colorectal cancer necessitates the supplementary application of cetuximab, a monoclonal antibody targeting EGFR." (PMID 39337479, 2024). "However, CDX2-suppressed colorectal cancers had a higher prevalence of mutations in alternative genes of the WNT/APC/β-catenin and KRAS/BRAF/MEK pathways." (PMID 39452477, 2024). "Herein, we report BRAF as a biomarker for response to BOLD-100 in colorectal cancer." (PMID 39083088, 2024). "The high presence of mutations such as BRAF in the right colon aligns with known patterns in colorectal cancer and indicates a sporadic pathway rather than Lynch syndrome." (PMID 39768914, 2024).
colorectal cancer (continued). "The potential interplay or distinct impact of mutations within the EGFR pathway (EGFR, KRAS, NRAS, BRAF, PI3KCA), along with polymorphisms in genes related to 5-fluorouracil and oxaliplatin (DPYD, TYMS, GSTP1, MTHFR, ABCB1), on the prognosis of colorectal cancer remains uncharted territory." (PMID 38248103, 2024). "Studies on PDCs and colorectal cancer report that a high number of PDCs in colon cancer are associated with the V600E mutation in the BRAF gene, although without statistical significance due to the limited number of cases collected." (PMID 39099686, 2024). "However, a study conducted in colorectal cancer demonstrated that the CCDC6::RET fusion is mutually exclusive with other important driver mutations, such as KRAS, BRAF and PIK3CA." (PMID 39684377, 2024). "Here, we found strong relation between BRAF mutations in colorectal cancer and expression of non-constitutive proteasomes." (PMID 38774235, 2024). "For example, ENO2 was involved in the oncogenic process of BRAF V600E colorectal cancer by regulating the MAPK/ERK signaling pathway and may be a novel therapeutic target for BRAF V600E mutant colorectal cancer." (PMID 38724951, 2024). "The reason for this could be that right-sided colorectal cancers often have a higher microsatellite instability (MSI) and BRAF mutation rate, while left-sided cancers are more associated with chromosomal instability pathways." (PMID 38711918, 2024). "Therefore, it is recommended to use combination approaches to improve the prognosis of patients with BRAF V600E colorectal cancer." (PMID 39555098, 2024). "Currently, TTF-1 expression is standard for NSCLC subtype differentiation and NGS for genetic background, but this is not sufficient for pulmonary metastases (especially thyroid and colorectal carcinomas, which are sometimes positive for TTF-1 and BRAF mutation)." (PMID 39767631, 2024). "For colorectal carcinoma, NTRK fusions are typically mutually exclusive of other mutations, thus the ideal scenario includes reflexive NTRK testing via NGS in all RAS/BRAF V600E wild-type, microsatellite instability (MSI)-high and mismatch repair deficient (dMMR)." (PMID 38200576, 2024). "Reports from Taiwan of KRAS wild-type colorectal cancer refractory to two or three regimens and from Italy of RAS/BRAF wild-type colorectal cancer refractory to two or three regimens both suggested that the therapeutic effect of anti-EGFR antibodies is better in left-sided colorectal cancer." (PMID 37760533, 2023). "Recent studies have found that aberrant DNA methylation occurs at early stages of colorectal cancer development and may sensitize colorectal cells to BRAF V600E-driven tumorigenic transformations into colorectal cancer." (PMID 37234978, 2023). "Colorectal cancers with BRAFV600E mutations are clinically different from tumours without BRAF mutations and also from tumours harbouring non-V600 mutations." (PMID 37466791, 2023). "Second, the consensus does not address the likely impact of the molecular genetics of colorectal cancer on surgical decision-making, for example, the evidence of poor outcome after hepatectomy in patients who carry the BRAF V600E mutation." (PMID 37442562, 2023). "Similarly, some institutions routinely test for BRAF variants, instead of or in addition to MLH1 promoter methylation, in colorectal cancer with MLH1/PMS2 loss by IHC." (PMID 38344144, 2023). "BRAF mutant colorectal cancer is a heterogeneous tumor subtype with variable efficacy for immune checkpoint blockade therapy, and the exploration of new predictive biomarkers for screening immunotherapy-sensitive populations other than MSI-H should continue to be encouraged." (PMID 37302081, 2023).
colorectal cancer (continued). "Higher tumour necrosis percentage associated with shorter colorectal cancer-specific survival independent of tumour grade, T, N or M-class, mismatch repair status, BRAF status, and other possible confounding factors." (PMID 37031328, 2023). "Elez et al1 recently showed the novel potential of RNF43 mutations to predict clinical benefit and favorable outcomes in patients with metastatic microsatellite stable (MSS) colorectal cancer (mCRC) and BRAFV600E mutated treated with anti-EGFR/BRAF combinatory regimens." (PMID 36779536, 2023). "It is common for BRAF mutations, especially BRAF V600E mutation, to be correlated with MSI in advanced colorectal cancer, which may be related to CpG island methylator phenotype and hypermethylation of MLH1 promoter." (PMID 37302081, 2023). "Despite the high mutation frequencies of KRAS, NRAS, and BRAF in colorectal cancer (CRC), there are no effective and reliable inhibitors for these biomarkers." (PMID 37063257, 2023). "BRAF non-V600 mutations are a distinct molecular subset of colorectal cancer (CRC) that has little to no clinical similarity to the BRAF V600 mutations." (PMID 37519790, 2023). "Together with the colorectal cancer data presented here, the association of genetic alterations including MSI-H, BRAF mutation, and KRAS mutations or MLH1 hypermethylation with Fn infection may be established during and/or after adenomacarcinoma transition." (PMID 37772997, 2023). "Furthermore, BRAF-driven colorectal cancer is one of the most poorly prognosed subtypes of colorectal cancer." (PMID 37685308, 2023). "BRAF-driven serrated colon cancers are among the most aggressive subsets of colorectal cancers." (PMID 38136364, 2023). "On the other hand, increasing Fn copy number in tissues was associated with increased probability to exhibit MSI-H, MLH1 hypermethylation or BRAF mutations but not KRAS mutations in colorectal cancer." (PMID 37772997, 2023). "Co-targeting this pathway using the FAK inhibitor PF562271 and the BRAF inhibitor vemurafenib could represent a promising therapeutic approach for BRAF-mutant colorectal cancer (CRC) patients, as they exhibit synergistic antitumor effects in vitro and in vivo." (PMID 37749625, 2023). "In a study by Flanagan, the Fn load between colorectal cancer with KRAS mutations and those with non-KRAS mutations, as well as colorectal cancer with BRAF mutations and those with non-KRAS mutations were compared." (PMID 37772997, 2023). "Given the putative regulation of CLDN4 by AP-1 through AP-1-binding sites in its promoter, mRNA expressions of CLDN4 within molecular subsets of colorectal cancers were examined taking into consideration the presence of mutations in the upstream regulators KRAS and BRAF." (PMID 37998722, 2023). "KRAS, NRAS, BRAF V600E Mutations, DNA Mismatch Repair Deficiency/Microsatellite Instability Status, HER2 Amplification, and NTRK Fusions are NCCN approved and actionable molecular biomarkers for colorectal cancer." (PMID 36980565, 2023). "In this study, we aimed to determine whether and how KRAS mutations are associated with Fn infection compared with the association of BRAF mutation, MLH1 hypermethylation and MSI-H with Fn using a previously characterized colorectal cancer cohort." (PMID 37772997, 2023). "BRAF mutations have strong bias to sporadic cases, and mostly can never be observed in hereditary colorectal cancer." (PMID 37190216, 2023). "To date, there is no specific association between PD-L1 expression and the efficacy of anti-PD-1/PD-L1 immunotherapy in colorectal cancer, but no data are available for the subset of BRAF mutations." (PMID 37302081, 2023). "Depending on the type of cancer, certain biomarker tests are needed in order to decide on a treatment strategy (e.g., RAS/BRAF testing for colorectal cancer; an HER2 testing for gastric cancer; and EGFR, ALK, ROS1, and PD-L1 expression testing for non-small-cell lung cancer)." (PMID 37599324, 2023).